RBM8A (RNA binding motif protein 8A)
Diseases named in the same sentence as RBM8A in open-access papers (continued):
Sharing a sentence is not in itself a finding about the gene and the disease.
tumor (continued). "We previously showed that the RBP RNA-binding motif protein 8A (RBM8A) is expressed in HCC tumor tissues at higher levels than in normal liver tissues." (PMID 33552961, 2020). "In that work, we also showed in vitro that RBM8A promotes tumor cell migration and invasion in HCC by activating the EMT signaling pathway." (PMID 30670676, 2019). "In addition, transwell migration and invasion assays showed that circEIF3H overexpression markedly ameliorated the tumor-suppressive effect of HSPD1/RBM8A/G3BP1 silencing." (PMID 35568705, 2022). "Besides, the protein expression of RBM8A was dramatically reduced in tumor xenograft tissues of mice after injection of Lv-sh1-RBM8A (P < 0.001)." (PMID 36105365, 2022). "In this work, we showed that overexpressed RBM8A promoted tumor cell growth in BC." (PMID 36105365, 2022). "DEGs may be affected by the high expression of RBM8A and may be involved in the ability of RBM8A to promote tumor growth and invasion." (PMID 34804926, 2021). "First, RBM8A-MAGOH polymerase activates NMD, eliminates mRNA containing nonsense mutations due to abnormal splicing, and enables normal transcriptional translation of tumor suppressor genes." (PMID 34326876, 2021). "We speculate that RBM8A plays an indirect role in tumor immunotherapy by targeting STAT3 to enhance the tumor immune response." (PMID 34326876, 2021). "Therefore, how does RBM8A, as a small part of an exon junction complex, influence tumor immunotherapy?" (PMID 34326876, 2021). "Our findings highlight the complexity of roles of RBM8A in tumor proliferation, which requires further investigation, which in turn may uncover additional prognostic biomarkers or therapeutic targets in the management of GBM." (PMID 34804926, 2021). "Moreover, the silencing of RBM8A inhibited the growth of tumor xenograft in vivo." (PMID 36105365, 2022). "Indeed, expression of RBM8A showed a positive correlation with GBM tumor purity in TCGA." (PMID 35573726, 2022). "The results of our analysis show that RBM8A is highly expressed in GBM and positively correlates with tumor purity." (PMID 35573726, 2022). "Gene array combined with bioinformatics analysis revealed that RBM8A has a wide range of transcriptional regulatory capabilities in drug-resistant HCC, including the ability to regulate several important tumor-related signaling pathways." (PMID 33552961, 2020). "Moreover, whole-genome microarrays combined with bioinformatics analysis revealed that RBM8A has a wide range of transcriptional regulatory capabilities in OXA-resistant HCC, including the ability to regulate several important tumor-related signaling pathways." (PMID 33552961, 2020). "Hence, we speculate that RBM8A influences patient survival in different cancers, especially LIHC, by acting on tumor cells through immunoinfiltrating cells and immune checkpoint inhibitors." (PMID 34326876, 2021).
cancer (16 papers, 2019 to 2024). A tumor composed of atypical neoplastic, often pleomorphic cells that invade other tissues. "Such profiling in other cancers has implicated RNA-binding motif protein 8A (RBM8A), a member of the RNA-binding motif protein (RBM) family." (PMID 35573726, 2022). "In this pan-cancer study, we used a database to comprehensively analyze the expression, mutation, and prognosis of RBM8A and obtained a series of corresponding results." (PMID 34326876, 2021). "This study aims to visualize the expression, prognosis, mutations, and coexpressed gene results of RBM8A across cancer types and to explore the link between RBM8A expression and immunity." (PMID 34326876, 2021). "COSMIC provided information on RBM8A mutations in various types of cancer, which included substitution missense mutations, synonymous mutations, and nonsense mutations, and the results are depicted in pie charts." (PMID 34326876, 2021). "In this pan-cancer study, we analyzed the expression, mutation, and prognosis of RBM8A using public sequencing data." (PMID 34326876, 2021). "Missense mutations in RBM8A were found in most tumors and affected the prognosis of carcinomas with coexpressed genes." (PMID 34326876, 2021). "The most important question, then, is whether mutations in RBM8A can affect the development of cancer." (PMID 34326876, 2021). "In addition to changes in the expression level of the RBM8A gene, this study also found that RBM8A mutations exist in most cancers." (PMID 34326876, 2021). "This work may contribute to elucidating the mechanism underlying RBM8A synthetic lethality in most cancer cell lines." (PMID 34944051, 2021). "In the first enriched pathway, surveillance pathway, five genes (HBS1L, DAZAP1, RBM8A, CSTF3, and CSTF2T) overlap, all of which have been previously implicated in cancer progression." (PMID 38305998, 2024). "The apoptotic defining characteristics featured abnormal centrosomes in cancer cells, supporting the importance of RBM8A in apoptosis regulation." (PMID 36142288, 2022). "CircEIF3H overexpression significantly promoted TNBC cell proliferation, Edu incorporation and colony formation in TNBC cells, and HSPD1/RBM8A/G3BP1 knockdown attenuated the cancer-promoting effect induced by the circEIF3H overexpression." (PMID 35568705, 2022). "Combined with existing research, we conclude that RBM8A is an immunotherapeutic agent that acts on the signaling pathway to regulate cancer." (PMID 34326876, 2021). "In summary, our study suggested that RBM8A mRNA is overexpressed in many types of cancer, and in combination with many different genes, RBM8A can influence the prognosis of cancer." (PMID 34326876, 2021). "Our research results are consistent with the current research results, further indicating that changes in the expression of the RBM8A gene are closely related to the occurrence of malignant tumors." (PMID 34326876, 2021). "Nevertheless, taken together, these data indicate that higher expression levels of RBM8A in MPM are paralleled by a more essential function of EJC in cancer cells when compared to mesothelial cells." (PMID 34944051, 2021). "Although the results of RBM8A in carcinomas provide a deeper understanding of cancer immune interactions and the potential models of cancer immunotherapy, the specific mechanisms remain to be further studied." (PMID 34326876, 2021). "Based on the results, we used the TIMER database to analyze the correlation between the expression of RBM8A and immune-infiltrating cells in multiple types of cancer to further examine the role of RBM8A in immunotherapy." (PMID 34326876, 2021). "Meanwhile, abnormal apoptotic centrosomes were also found in cancer cells after the expression of RBM8A was inhibited." (PMID 32294703, 2020). "Abnormal expression of RBM8A was first detected in cervical cancer, and its overexpression was subsequently detected in various malignant tumors, including non-small cell lung cancer and myeloma." (PMID 30670676, 2019).
cancer (continued). "Therefore, there is a possibility of adverse effects when RPS3, EIF2S1 and/or RBM8A are targeted in cancer therapy." (PMID 34202873, 2021). "In addition to normal tissues and immune cells, many studies have found that RBM8A is highly expressed in certain cancer tissues." (PMID 34326876, 2021). "The RNA-binding motif protein 8A (RBM8A) has different effects on various human cancers." (PMID 34804926, 2021). "In addition to TAR, changes in the level of RBM8A expression can also lead to the occurrence of some types of cancer and affect their prognosis." (PMID 34326876, 2021). "Our study found that RBM8A may interact with immune-infiltrating cells through signaling pathways in cancer and simultaneously influence immune checkpoints to regulate the occurrence of immune responses." (PMID 34326876, 2021). "However, the role of RBM8A and immunity across cancer types is unclear." (PMID 34326876, 2021). "Functional network analysis showed that in HCC, the expression of RBM8A was involved in ribosomal signal transduction, RNA transport, mRNA monitoring, and spliceosome signaling and regulated DNA replication, repair, and cell cycle progression through cancer-related kinases." (PMID 34326876, 2021). "Therefore, we speculate that RBM8A may be a promising target in cancer immunotherapy, especially in LIHC." (PMID 34326876, 2021). "Therefore, it is important to expand the research on the role of RBM8A in cancer." (PMID 34326876, 2021). "Therefore, we consider that RBM8A may be a promising target in cancer immunotherapy." (PMID 34326876, 2021). "In recent years, an increasing number of studies have been conducted on RBM8A and cancers, but no integrative pan-cancer analysis of RBM8A has been found thus far." (PMID 34326876, 2021). "We indeed observed a modest decrease in RBM8A protein in cancer MCF-7 cells compared to non-cancerous MCF-10A cells." (PMID 34204574, 2021). "The results showed that the RBM8A mutant gene had no significance with the 6 infiltrated cells in the pan-cancers." (PMID 34326876, 2021). "Remarkably, we could recapitulate cancer-specific mRNA re-splicing in normal cells by knock-down of any of the core EJC proteins, EIF4A3, MAGOH, or RBM8A (Y14), implicating the EJC core as the repressor of mRNA re-splicing often observed in cancer cells." (PMID 34204574, 2021). "Although the expression of RBM8A in other cancers has been investigated, the expression and biologic roles of RBM8A in GC have not been reported." (PMID 32294703, 2020). "Our functional assay showed that growth suppression was induced in non-cancerous cells by the downregulation of three RBPs (RPS3, EIF2S1, RBM8A), suggesting that these molecules have pivotal functions in proliferation and apoptosis in non-cancerous cells as well as cancer cells." (PMID 34202873, 2021). "RNA binding motif protein 8A (RBM8A), also known as Y14, is an essential factor in exon junction complex (EJC), translation, chromatin remodeling, damage checkpoints, regulation of apoptosis, and deregulation contribute to cancer pathologies and cardiovascular diseases." (PMID 33692831, 2021). "However, there are very few experimental studies and relevant data on RBM8A and cancer, and no studies on RBM8A and the different types of carcinomas have been found; thus, the mechanism of action is unclear." (PMID 34326876, 2021).
neurodevelopmental disorder (4 papers, 2015 to 2024). A behavioral and cognitive disorder with onset during the developmental period that involves impaired or aberrant development of intellectual, motor, or social functions. "CNVs targeting the 1q21.1 region where the RBM8A gene is located have previously been associated with neurodevelopmental disorders, including ASD." (PMID 35327467, 2022). "For instance, loss-of-function mutations in UPF2, UPF3B, SMG8 and SMG9 genes, and CNVs targeting UPF2, UPF3A, SMG6, EIF4A3, RNPS1 and RBM8A genes, have been implicated in a variety of neurodevelopmental disorders, including DD, ID, ADHD and TAR syndrome." (PMID 35327467, 2022). "As duplication of 1q21 region has also been implicated in neurodevelopmental disorders, the reduced proliferation by RBM8a knockdown encouraged us to pursue the reciprocal RBM8a gain-of-function experiment." (PMID 26094033, 2015). "Moreover, the alteration in astrocyte density underlines the significance of RBM8A in central nervous system pathology, offering new perspectives on neurodevelopmental disorders through astrocytic involvement." (PMID 38534343, 2024). "This study further reveals the contribution of Rbm8a deletion to CNS pathology, generating more insights via the glial lens of an Rbm8a model of neurodevelopmental disorder." (PMID 38534343, 2024). "The role of RNA Binding Motif Protein 8a (RBM8A), an exon junction complex (EJC) component, in neurodevelopmental disorders has been increasingly studied for its crucial role in regulating multiple levels of gene expression." (PMID 38534343, 2024). "Studies of RBM8a and other NMD factors in embryonic brain development may help understand the pathophysiology of several neurodevelopmental disorders such as ID, ASD and SCZ." (PMID 26094033, 2015).
psychiatric disease (3 papers, 2015 to 2021). "These processes were those found to be abnormal in our overexpression and knockdown experiments, indicating an important role for RBM8a in neural development, and the risk for neurological and psychiatric disease." (PMID 26094033, 2015). "As RBM8a is localized in 1q21 region, our studies provide an insight on causes of mental illnesses and will facilitate the development of new targets for neurodevelopmental illnesses." (PMID 26094033, 2015). "These genetic indications of RBM8A’s role in psychiatric disease are especially interesting in light of the neurogenesis and cell migration deficits associated with Nes-cre; RBM8afl/+ mice." (PMID 33154347, 2020).
neurological diseases (2 papers, 2019 to 2020). "Thus, our study on the Rbm8a cKO mice may further reveal its potential role contributing to the pathogenesis of neurological diseases." (PMID 33154347, 2020). "Our previous studies revealed RBM8A may play a role in various progressive neurological diseases." (PMID 31816601, 2019).
hematologic disorder (1 paper, 2022). A disease involving the hematopoietic system. "The same could be said for cases with CNVs affecting RBM8A (enriched in blood) and hematologic disorders." (PMID 35457073, 2022).
neurodegenerative disease (1 paper, 2024). A disorder of the central nervous system characterized by gradual and progressive loss of neural tissue and neurologic function. "It has been shown that RBM8A and other genes located in the 1q21.1 copy number variant are associated with neurodevelopmental and neurodegenerative disease, and especially with ASDs and ID." (PMID 38534343, 2024).
RBM8A also shares sentences with these, for which no sentence is quoted: colon cancer (2 papers); esophageal cancer (2); Intellectual disability (2); 21-hydroxylase deficiency (1); adrenocortical carcinoma (1); amyotrophic lateral sclerosis (1); Bardet-Biedl syndrome (1); biotinidase deficiency (1); bladder cancer (1); breast invasive carcinoma (1); cardiovascular diseases (1); cervical squamous cell carcinoma (1); cervical tumor (1); cholangiocarcinoma (1); colon adenocarcinoma (1); colorectal cancer (1); COVID-19 (1); cystic fibrosis (1); depression (1); endometrial carcinoma (1); epilepsy (1); esophageal adenocarcinoma (1); esophageal squamous cell carcinoma (1); frontotemporal dementia (1); glycogen storage disease II (1); gray platelet syndrome (1); head neck squamous cell carcinoma (1); Hepatitis B (1); Hypertension (1); Hypotonia (1).
A further 27 diseases each share a sentence with RBM8A in 1 paper.